RN7SL283P (RNA, 7SL, cytoplasmic 283, pseudogene)
Gene: Miscellaneous RNA gene on chromosome 2 (139,982,684 to 139,982,986, forward strand). Ensembl gene ENSG00000240977.
Homologues: Orthologues: chimpanzee Metazoa_SRP (86% identical). Paralogues in human: RN7SL5P (69% identical), RN7SL15P (68% identical), RN7SL2 (68% identical), RN7SL33P (68% identical), RN7SL88P (68% identical), RN7SL1 (67% identical), RN7SL617P (67% identical), RN7SL665P (67% identical), RN7SL3 (67% identical), RN7SL329P (67% identical), RN7SL408P (67% identical), RN7SL804P (67% identical), and 699 more.